ISG15 (ISG15 ubiquitin like modifier)
Diseases named in the same sentence as ISG15 in open-access papers (continued):
Sharing a sentence is not in itself a finding about the gene and the disease.
COVID-19 (continued). "The interferon-stimulated gene ISG15 stands out as having the highest fold change in severe COVID-19 patients and is strongly represented in the three other COVID-19 scRNAseq studies." (PMID 38107402, 2023). "The interferon (IFN)-stimulated 15 KDa protein (ISG15) had the largest increase in serum of COVID-19 patients, followed by several other IFN-induced proteins, such as ILF2, MX1, ISG20, LAP3, and UBE2L6." (PMID 37739942, 2023). "Our study investigated IFN-I driven inflammation and found that the IFN-I responsive genes (e.g., ISG15 and IFITM1/2/3, etc.)and associated-GO pathways were enriched in COVID-19 patients with acute necrotizing encephalopathy." (PMID 37848421, 2023). "Since MX1, MX2, ISG15, and OAS1 showed a similar expression pattern in COVID-19-positive patients, we next evaluated the association of their combined expressions with viral load." (PMID 36298734, 2022). "An increase in ISG15 in the nasopharyngeal in SARS-CoV-2 positive patients was observed in this study, which is consistent with the increased ISG15 in the serum of patients with COVID-19 in other studies." (PMID 36094909, 2022). "Recently, a multiomics analysis in a model of severe COVID-19 also highlighted the importance of ISG-15 in the overall antiviral response, particularly in the lungs." (PMID 35842415, 2022). "Conventional ISGs, such as IFI6, IFI44L, LY6E, and ISG15, were markedly increased in COVID-19 patients compared to healthy controls across all major cell types in PBMCs." (PMID 35064122, 2022). "Previous work has shown increased expression of IFITM3 in platelets from COVID-19 patients; our dataset includes the differential abundance of ISG15 and IFITM1, reinforcing the importance of platelets in antiviral response." (PMID 35842415, 2022). "IFI6 has a higher expression in moderate respect to severe COVID-19 patients, whereas ISG15 behaves viceversa." (PMID 34603282, 2021). "One study showed increased classical CD14+HLA-DRhi monocytes with high IFI6 and ISG15 expression in mild COVID-19 cases when compared to healthy controls, similar to our findings." (PMID 34108966, 2021). "Nonetheless, we were able to corroborate that LL-37, HMGB1 and ISG-15 are expressed in NETs from COVID-19 patients by confocal microscopy." (PMID 34685525, 2021). "Accordingly, we found an increased expression of ISG-15 in NETs from pooled data of all included COVID-19 patients in comparison to healthy donors." (PMID 34685525, 2021). "Nonetheless, when we compared the amount of 1SG-15-DNA circulating complexes, we found lower levels of ISG-15-DNA complexes in severe COVID-19." (PMID 34685525, 2021). "When we analyzed DEGs, severe COVID-19 was characterized by up-regulation of various ISGs, including ISG15, IFITM1/2/3, and ISG20." (PMID 32651212, 2020). "The difference between our results and theirs in relation to ISG15 may be attributable to ISG15 expression in severe COVID-19 patients." (PMID 38580667, 2024). "Besides, quercetin’s role in mediating proliferation and migration of tumor cells in UCEC patients with COVID-19 through ISG15-related pathways needs to be further explored." (PMID 36969077, 2023). "Of note, we observed a localized downregulation of certain complement factors (C1QB, CFD, and C7) and interferon response genes (IFI6 and ISG15), in contrast to their enrichment in COVID-19 lungs compared to control lungs in our samples and in others analyzed in previous works." (PMID 37858234, 2023). "Given their responsiveness to IFN signaling, ISG15 and its downstream targets, including MX1156, have been implicated as key participants during SARS-CoV-2 infection by using in vitro and in vivo models as well as samples from COVID-19 patients." (PMID 37016066, 2023).
COVID-19 (continued). "Dexamethasone strongly inhibited plasma ISG15 concentration in patients with COVID-19, and thus demonstrated the capability of modulating cytokines and transcription factors that play a role in the antiviral host response but are also linked to cytokine hyperresponsiveness." (PMID 37614228, 2023). "ISG15 was downregulated in samples with two doses of adenovirus or attenuated vaccination and upregulated in controls, reflecting the protective ability of COVID-19 vaccination on target cells." (PMID 37007947, 2023). "In line with our findings, CD14hiCD16hi cells and AMs enriched with viral RNA in autopsy lungs of COVID-19 patients also had distinct transcriptomes which were largely recapitulated in what we construe as CXCL10-associated genes (CXCL11, CCL18, CCL8, ISG15, CD83)." (PMID 35483404, 2022). "Analysis of type I IFNs inducible genes expression performed in granulocytes and PBMCs showed increased transcription of ISG15 and IFIT1 mRNAs in cells of the COVID-19 patients, while ISG15 and IFIT1 mRNAs were detected in MIS-C at levels comparable to adult healthy controls." (PMID 33841438, 2021). "Amongst the top genes we see altered in COVID-19 is the interferon response protein ISG15, which is also known to be a direct target of the SARS-CoV-2 NSP3 protease for the removal of ISGylation from target proteins such as the MDA5 sensor that can regulate the intracellular IFN response by viruses." (PMID 34335605, 2021). "Although expanded PBs were clearly linked to plasma autoantibodies in our patients, we found evidence that not the PBs themselves, but atypical B cells with low T-bet expression as well as CD80+/ISG15+ memory B cells harbor immunogenetic and transcriptional signs of autoreactivity in COVID-19." (PMID 34723157, 2021). "Conversely, circulating ISG-15-DNA complexes were lower in patients with severe COVID-19." (PMID 34685525, 2021). "Moreover, COVID-19 neutrophils expressed higher amounts of ISG15 and decreased levels of suppressor of cytokine signaling 3 (SOCS3) mRNA upon IFNα stimulation." (PMID 33003471, 2020). "Genes enriched in male Mo/DCs relative to female Mo/DCs included multiple ISGs (IFI27, IFI6, and ISG15), prompting us to perform an upstream regulator analysis to identify cytokines predicted to promote sex-biased Mo/DC gene expression patterns in patients with COVID-19." (PMID 37606044, 2023). "Thus, the expression of ISG15 on alveolar epithelial cells may reflect virus-induced damage, helping to compare the protective capacity of COVID-19 vaccines." (PMID 37007947, 2023). "Consistently, genes (e.g., ISG15, IFITM1/2/3, OAS3 and IFIT1/2/3) associated with the IFN-response pathway, especially for IFN-I response, were significantly upregulated in COVID-19 associated acute necrotizing encephalopathy compared with healthy donors and other COVID-19 groups." (PMID 37848421, 2023). "Our study found that the high expression of IFN-β in COVID-19 patients induced an increase in ISG15 and a high expression of IFIT1 (ISG56), the main subclass of ISG proteins with broad-spectrum antiviral activity, which may be the antiviral immune mechanism induced by SARS-CoV-2 infection." (PMID 35632738, 2022). "Meanwhile, high expression of ISG15 in NK cells, as an interferon-stimulating factor (ISG), was commonly associated with viral RNA perception of critical patients, and our results suggested that the intensity of interferon response was related to the severity of patients with COVID-19." (PMID 35911765, 2022). "The identification of IFIT1, IFITM1, IRF7, ISG15, MX1, and OAS2 as pivotal components suggested their viability as potential drug targets for COVID-19." (PMID 40552037, 2025). "Elevated IFI44L, ISG15, and OAS1 mirror transcriptomic patterns reported in psoriatic arthritis and severe COVID-19, suggesting convergent antiviral-like activation." (PMID 40869237, 2025).
COVID-19 (continued). "This was characterized by low levels of IRF7, IFNβ1, ISG15 and IFNγ, highlighting the importance of intact TLR7 signaling in the pathogenesis of severe COVID-19." (PMID 41011507, 2025). "In line with this, elevated protein levels of ISG15 and MX1 have been found in the sera of COVID-19 patients, while increased protein levels of MX1 were found in the placental proteome profiles of women with lupus." (PMID 40574053, 2025). "In this study, the highest differentially expressed genes in COVID-19 (+) tissue, including ISG15 itself, IFIT1, RSAD2, OAS1, MX1, OASL, and IFIT3, are all important for the ISG15 pathway’s progression and are part of the lung tissue’s antiviral response." (PMID 38932146, 2024). "Specifically, in COVID-19, these genes were CD52, ISG15, and MMP9; in influenza, they included IFI44L, IFIT3, ISG15, and OAS1; and in HIV, OAS1 was identified." (PMID 38601162, 2024). "Several IFN-related genes, such as SPATS2L, OAS2, ISG15, ZBP1, and IFI44L, exhibited similar patterns of upregulation across both dengue and COVID-19 datasets, while others, such as AIM2 and RTP4, showed distinct regulation." (PMID 38444851, 2024). "IFN-related genes, such as ISG15, IFITM1 and GBP4, were also downregulated in B_naive and B_activated of severe compared to moderate COVID-19." (PMID 37095364, 2023). "Although they were not enriched in autoreactive B cells, two distinct memory populations (CD80+/ISG15+ and CD11c+/SOX5+/T-bet+/−) with signs of autoreactivity were identified, which were considered to be the source of COVID-19 autoantibodies." (PMID 37243231, 2023). "Interferon response genes, including ISG15 and BST2, had increased expression in the same groups that also had p-PBs (adults with COVID-19, children with dengue)." (PMID 37638019, 2023). "As an indication of disease severity, we measured the mRNA expression levels of IFN-stimulated genes (IFIT1, IFIT3, ISG15, and MX2), pro-inflammatory cytokines (IL6, IL10), and chemokines (CXCL10, CCL2) that are correlated with COVID-19 exacerbation." (PMID 35562337, 2022). "Western blot analyses showed significant expression of ISG-15 and IFITM-1, in line with proteomic results showing these EPs from the COVID-19 group." (PMID 35842415, 2022). "The interferon-related genes IFNB1, ISG15, and IFIT1 were also activated in COVID-19 patients, and GO analysis showed that HERV-K (HML-2) can regulate the secretion of interferon." (PMID 35632738, 2022). "Upregulated genes in early COVID-19 mortality included many involved with interferon signaling (e.g., GBP2, ISG15), the NF-κB pathway (e.g., NFKB2, NFKBIA), and TNF-α and IL-1 signaling (e.g., TANK, NOD1, RELA)." (PMID 35446789, 2022). "In large airway tissues, genes related to the mucosal layer (MUC4, MUC5AC, MUC5B) as well as cytokine-mediated signaling pathway genes (CCL20, CXCL1, CXCL6, CXCL6, MMP1) and type I interferon genes (IFIT3, ISG15, STAT1, MX1) were upregulated in COVID-19." (PMID 35233546, 2022). "ISG15, STAT1 and MX1 are the most conserved up-regulated genes across COVID-19 datasets of immunological cells." (PMID 36553678, 2022). "Another study also reported increased interferon signaling genes including IFI44L, IFIT1, IFIT3 and ISG15, in CD16+ monocytes in COVID-19 cases compared to healthy controls." (PMID 34108966, 2021). "We found that COVID-19 NETs have a higher expression of HMGB1, LL-37 and ISG-15 in comparison with healthy donors." (PMID 34685525, 2021). "When we evaluated the NET protein cargo by confocal microscopy, LDG and NDG from COVID-19 patients showed a higher expression of HMGB1, ISG-15 and LL-37 in comparison with healthy donors." (PMID 34685525, 2021). "Genes involved in antiviral activity (i.e., ISG15, MX1, OAS1) and hyper-responsiveness of the immune system (i.e., TNFAIP8L2) were over-expressed in neutrophils from deceased COVID-19 patients." (PMID 34012444, 2021).
COVID-19 (continued). "Severe/critical COVID-19 patients had higher plasmatic NE, LL-37 and HMGB1-DNA complexes, whilst ISG-15-DNA complexes were lower in severe patients." (PMID 34685525, 2021). "In our study, we report that IRF7, ISG15, IFI44L, IFIT1, and IFIT3 gene expression is increased in CD16+ monocytes from people with mild COVID-19 compared to healthy controls." (PMID 34108966, 2021). "We found that COVID-19 neutrophils displayed higher basal level of IFNα, IFIT1, and ISG15 mRNA compared to COVID-19 PBMCs, healthy donor PBMCs, and healthy donor neutrophils." (PMID 33003471, 2020). "The identification of key immune-modulating genes like ISG15, SERPING1, C1QA, C1QB, and VSIG4 opens avenues for therapeutic approaches that aim to modulate the immune response and improve outcomes in severe COVID-19 cases via upregulation of expression of these genes." (PMID 40374692, 2025). "Currently, to our knowledge, no therapies for COVID-19 or other infectious diseases have been developed that specifically target ISG15, SERPING1, or VSIG4 genes." (PMID 40374692, 2025). "ISGs, such as IFIT and IFITM, ISG15, IFIH1, MX1, IRF7, OAS 1-3, and STAT1 are recognized for enhancing IFN signaling, thereby contributing to antiviral activity, emerge as potential candidates for drug targets in COVID-19 treatment." (PMID 40552037, 2025). "Extracellular ISG15 acts as a ligand for integrin ITGAL38, interacting with it and stimulating release of IFNγ and IL10 from NK cells through that interaction, with expression of IL10 being especially notable as an important factor in COVID-19 prognosis." (PMID 40374692, 2025). "For instance, ISG15, an interferon-stimulated gene, is massively released by macrophages during SARS-CoV-2 infection, amplifying pro-inflammatory cytokine and chemokine secretion and potentially contributing to hyperinflammatory responses in COVID-19." (PMID 41039310, 2025). "For instance, extracellular ISG15 has been found to be highly secreted after SARS-CoV-2 infection in in vitro models and identified as one of the most highly expressed proteins detected in the serum and plasma of COVID-19 patients." (PMID 40719862, 2025). "In addition, the expression of VANGL2 presented a reverse correlation with IFITM3, ISG15, GBP1, and TRIM27, which have been reported to play important roles in antiviral immunity in the COVID-19 patients’ database." (PMID 37352355, 2023). "Inflammatory-related genes, such as ISG15 and IFI27, were upregulated in COVID-19 patients." (PMID 36732528, 2023). "In addition, IPIN analysis from COVID-19 patient lung tissue revealed that IFIH1, DDX58, ISG15, OASL, and XAF1 were hub genes in the network." (PMID 35625619, 2022). "Classical monocytes in severe COVID-19 were found to be accompanied by the IFN-I response that was characterized by the up-regulation of various interferon-stimulating genes (ISGs), including ISG15, IFITM1/2/3, ISG20, IFI27, and MX1 when compared to mild COVID-19." (PMID 36159873, 2022). "Although both subtypes are significantly up-regulated in the plasma of COVID-19 patients, only IFNA2 levels correlate with the IFN-α scores and with mRNA expression of well recognized IFN-inducible genes (ISGs), such as ISG15 and OAS2." (PMID 35217532, 2022). "Notably, type I IFNs led to a significant increase in IRF3, ISG15, and IFI6 expressions in convalescent COVID-19 patients compared to healthy controls, suggesting a higher degree of activation." (PMID 35464396, 2022). "Furthermore, results evidenced that COVID-19-positive patients with higher expressions of JAK2 and STAT1 showed increased MX1, MX2, ISG15, and OAS1 mRNA levels." (PMID 36298734, 2022). "IFI44, OAS1, IFI44L, ISG15, and HERC5 are the five hub genes shared by RA, COVID-19, and SAB." (PMID 36189314, 2022).
COVID-19 (continued). "Specifically, the NK2.1 cells of elderly patients have high expression of genes with functional annotations related to response to type I interferon (e.g. ISG15, ISG20, etc.)compared to that of NK2.1 cells from young COVID-19 patients (P = 1.11e−36, Wilcoxon rank-sum test)." (PMID 35501841, 2022). "Circulating NETs containing ISG-15, LL-37, and HMGB1 are detected in patients with COVID-19." (PMID 34685525, 2021). "Although the analysis was limited to only two patients without individual cell-type resolution, in genome browser, up-regulation of IFITM1, ISG15, and JAK3 and down-regulation of RPS18 were observed commonly in post-mortem COVID-19 lung tissues and classical monocytes of severe COVID-19." (PMID 32651212, 2020). "It will also be valuable to determine whether ISG15 expression differs between those with and without long COVID-19 symptoms." (PMID 38580667, 2024). "These DE genes at D1 enriched for viral response pathways from the Reactome database, including “ISG15 antiviral mechanism”, “Interferon signaling”, “Interferon-γ signaling”, and “Interferon α/β signaling”, which were all upregulated at D1 in COVID-19 patients vs. non-COVID-19 sepsis patients." (PMID 37090709, 2023). "Among prominent ones are CXCL10, a marker of acute viral infection, ISG15, both an extracellular cytokine and an intracellular protein modifier, IFI6 that may be involved in the regulation of cell apoptosis and IFI27, a proven predictor for COVID-19 outcomes." (PMID 37685932, 2023). "Hence, the in-silico validation of our hub genes in those expression datasets pointed out that ISG15 and MX1 are the most conserved up-regulated genes across COVID-19 datasets of immunological cells, while OAS1 and MX1 are those with lower gene expression levels in tissue-specific healthy samples." (PMID 36553678, 2022). "Patients with COVID-19 show a diminished type I Interferon signature in PBMCs, but neutrophils from these patients have an enhanced expression of interferon-related genes including IFNα, IFIT1 and ISG-15 which agrees with our finding of a higher amount of ISG-15 expressed in NETs." (PMID 34685525, 2021). "The intermediate monocytes (consistently present in COVID-19) were characterized by a pronounced antiviral, interferon-driven response, as illustrated by the upregulation of both interferon-inducible and stimulated genes (IFI6, IFI27, IFI44L, and ISG15, SIGLEC1)." (PMID 34424199, 2021). "nsp3 catalyzes the reaction that preferentially cleaves ubiquitin-like interferon-stimulated gene 15 (ISG15) protein from interferon factor 3 (IRF3) which weakens the type I interferon response, could exacerbate hyperinflammatory conditions and progression to severe COVID-19." (PMID 36318347, 2022). "Expression of MX1, MX2, ISG15, and OAS1 (four well-known IFN-stimulated genes (ISGs)) displayed upregulation in COVID-19-positive vs. -negative patients." (PMID 36298734, 2022). "IFI6, ISG15, IFI27, and IFI35 were increased in mild, and decreased or not changed in severe COVID-19, compared to healthy controls." (PMID 34108966, 2021). "Targeted proteomics to measure abundance levels of MX1, ISG15, STAT1, RIG-I, and CXCL10 detected proteomic signatures of interferon-mediated antiviral signaling that differentiated COVID-19-positive from COVID-19-negative cases." (PMID 34400346, 2021). "Notably, in the present work, we demonstrated that the expressions of the ISGs MX1, MX2, ISG15, and OAS1 were upregulated in COVID-19-positive vs. -negative patients." (PMID 36298734, 2022). "Through an increased concentration of non-conjugated ISG15 in macrophages, SARS-CoV-2 has been shown to induce a pro-inflammatory response that could contribute to the excessive proinflammatory cytokine response and related immunopathogenesis in severe COVID-19." (PMID 37614228, 2023).